GLP1R (glucagon like peptide 1 receptor)
Diseases named in the same sentence as GLP1R in open-access papers (continued):
Sharing a sentence is not in itself a finding about the gene and the disease.
heart failure (172 papers, 2011 to 2026). Inability of the heart to pump blood at an adequate rate to meet tissue metabolic requirements. "In this MR study, we used human genetic data to identify proxies for GLP1R agonism and found evidence for their protective effect on risk of heart failure." (PMID 34184541, 2021). "Several large placebo-controlled trials in patients with T2D and cardiovascular disease have shown that GLP‐1R agonists, such as semaglutide, have a neutral effect on reducing risk for heart failure hospitalization." (PMID 33397369, 2021). "In conclusion, we identified genetic proxies for the effects of GLP1R agonism, and applied these proxies in MR analyses to generate evidence supporting a protective effect on risk of heart failure." (PMID 34184541, 2021). "Genetically proxied GLP1R agonism associated with a reduced risk of heart failure (odds ratio [OR] per 1 mmol/mol decrease in glycated hemoglobin, 0.75; 95% CI, 0.64–0.87; P=1.69×10−4)." (PMID 34184541, 2021). "The novel dual incretin analogue tirzepatide was shown to have superior effects compared to GLP-1R agonists in terms of weight loss, and tirzepatide was the first incretin analogue to show improved cardiovascular outcomes in a heart failure trial, however, so far only in patients with HFpEF." (PMID 40517248, 2025). "On the other hand, GLP-1R agonists don’t affect the risk of heart failure (HF)." (PMID 32384887, 2020). "The aim of this study was to leverage human genetic data within the Mendelian randomization paradigm to investigate whether effects of GLP1R agonists on heart failure risk and left ventricular ejection fraction (LVEF) exceed those of improved glycemic control more generally." (PMID 34184541, 2021). "CV, cardiovascular; GLP-1RA, glucagon-like peptide-1 receptor agonist; HFpEF, heart failure with preserved ejection fraction; HFrEF, heart failure with reduced ejection fraction; MI, myocardial infarction; SGLT2i, sodium-glucose cotransporter 2 inhibitor." (PMID 39548500, 2024). "In this regard, the broader availability of sodium–glucose cotransporter 2 inhibitors and glucagon-like peptide 1 receptor agonists can allow tailored treatments, particularly for those with heart failure and chronic kidney disease as comorbidities." (PMID 38625582, 2024). "Our literature search also indicated that collectively, 15 urinary peptides downregulated by GLP-1R agonists in our study (originating mainly from the collagen protein family), when upregulated, had been previously reported as markers of heart failure." (PMID 37686344, 2023). "High expression of GLP-1r agonist has been reported to reduce cardiovascular events such as heart failure and atherosclerosis in diabetic patients." (PMID 37885997, 2023). "that included data from all of these studies demonstrated a significant reduction in hospitalisation for heart failure in patients treated with GLP1R agonists relative to placebo (HR 0.88 (95% CI 0.82–0.94))." (PMID 34097240, 2022). "Nevertheless, more strong evidence on glucagon-like peptide-1 receptor agonists in heart failure is required." (PMID 35813629, 2022). "The magnitude of these estimates exceeded those generated using genetic proxies for glycemic control more generally, supporting a role for GLP1R signaling in preventing heart failure beyond an effect on glycemic control alone." (PMID 34184541, 2021). "Further investigation of GLP1R agonist repurposing to prevent heart failure in the context of clinical trials is warranted." (PMID 34184541, 2021). "Ongoing studies are examining the effects of administering GLP-1R agonists to patients at risk of CVD, postangioplasty patients, post-CABG patients, and patients with heart failure." (PMID 21167014, 2012). "Although exenatide clearly has complex effects in heart failure, the expression of the G-protein-coupled receptor GLP-1R in cardiomyocytes supports the role of a direct effect on the heart." (PMID 21359201, 2011).
heart failure (continued). "We used relevant articles to gather controlled vocabulary and potential synonyms to formulate a search strategy for the following concepts: heart failure with preserved ejection fraction, glucagon-like peptide-1 receptor agonists, and sodium-glucose cotransporter-2 inhibitors." (PMID 40062142, 2025). "GPCR drug development has led toimportant cardiovascular therapies, such as antagonists of β-adrenergicand angiotensin II receptors for heart failure and hypertension, and agonists ofthe glucagon-like peptide-1 receptor for reducing adverse cardiovascular eventsand other emerging indications." (PMID 38900852, 2024). "This study was designed to investigate the genetic evidence for repurposing of GLP1R (glucagon‐like peptide‐1 receptor) agonists to prevent heart failure (HF) and whether the potential benefit exceeds the benefit conferred by more general glycemic control." (PMID 34184541, 2021). "The null effect of genetically proxied GLP1R agonism on coronary artery disease risk suggests that a reduced risk of heart failure is not attributable to chronic ischemic heart disease." (PMID 34184541, 2021). "In the last few years, hypoglycaemic drugs, such as sodium-glucose co-transporter 2 inhibitors and glucagon-like peptide-1 receptor agonists, demonstrated a cardioprotective effect, mainly in terms of decreasing hospitalization for heart failure and cardiovascular death in type 2 diabetic patients." (PMID 31212945, 2019). "In case of established CVD, a combination of glucagon-like peptide-1 receptor agonist with proven CV benefits is recommended along with metformin, while for chronic kidney disease or heart failure, a sodium–glucose transporter proteins-2 inhibitor with proven benefit is advised." (PMID 31572499, 2019). "However, the effects of GLP-1R agonists in heart failure remain controversial." (PMID 39462311, 2024). "Glucagon-like peptide-1 receptor agonists (GLP-1 RAs) have shown cardiovascular (CV) benefits, but their effects across the heart failure (HF) spectrum remain uncertain." (PMID 42292722, 2026). "Landmark trials such as EMPA‐REG OUTCOME (2015) and DAPA‐HF (2019) demonstrated reductions in heart failure hospitalizations, and the LEADER trial (2016) showed decreased cardiovascular mortality with glucagon-like peptide-1 receptor agonists (GLP‐1 RAs)." (PMID 40821258, 2025). "Further studies investigating the cardiac effects of incretin analogues and comparison of GLP-1R agonists and dual GLP-1R/GIPR agonists are needed to better understand the potential benefits and risks of incretin analogue therapy in heart failure." (PMID 40517248, 2025). "Protection against macrovascular outcomes has been found to be even greater with use of newer antidiabetic agents such as sodium-glucose cotransporter 2 (SGLT2) inhibitors and glucagon-like peptide-1 receptor agonists (GLP1-RA), particularly for heart failure." (PMID 36899347, 2023). "Sodium–glucose cotransporter 2 inhibitors (SGLT2i) and glucagon-like peptide-1 receptor agonists (GLP-1RAs) are now accepted as the best therapeutic option for patients with T2DM and cardiovascular disease, heart failure and/or chronic kidney disease." (PMID 35096933, 2021). "As such, SGLT2 inhibitors and GLP-1R agonists to an extent, have been shown to reduce cardiovascular events in people with T2DM, while also reducing hospitalization rates for heart failure." (PMID 33364978, 2020). "Semaglutide, a glucagon-like peptide-1 receptor agonist (GLP-1 RA), exerts a multifaceted mechanism of action that aligns with the metabolic, inflammatory, and hemodynamic challenges of heart failure with preserved ejection fraction (HFpEF), particularly in patients with obesity and T2D." (PMID 40786355, 2025). "In the FIGHT and LIVE trials, GLP-1R agonists did not lead to significant improvements in left ventricular systolic function, heart failure rehospitalizations, or overall survival." (PMID 39462311, 2024).
heart failure (continued). "The existing literature appears to hold promise that GLP-1R agonists and DPP-4 inhibitors might exert cardioprotective effects beyond glycemic control in patients with hypertension and heart failure." (PMID 36771035, 2023). "The impact of glucagon-like peptide-1 receptor agonists on patients with heart failure has not been fully described." (PMID 35813629, 2022). "Cardiovascular outcome studies of GLP-1R agonists do not affect the rate of heart failure hospitalization, while decreasing the rate of myocardial infarction and stroke." (PMID 32384887, 2020). "Our analysis, based on > 33,000 patients and 4000 cardiovascular events, provided robust reassurance about the cardiovascular safety of GLP1R agonists, showing no increase in risks for hospitalization for heart failure and myocardial infarction." (PMID 30223891, 2018). "The effects of GLP-1R agonists have also been studied in models of MI (ischemia with or without reperfusion) and heart failure (HF)." (PMID 21167014, 2012). "The impressive results of recent clinical trials with glucagon-like peptide-1 receptor agonists (GLP-1Ra) and sodium glucose transporter 2 inhibitors (SGLT-2i) in terms of cardiovascular protection prompted a huge interest in these agents for heart failure (HF) prevention and treatment." (PMID 34583699, 2021). "The same holds true for GLP1-R: for example, miRNA-665 downregulates GLP1-R in the hearts of rats with heart failure, and this mechanism may explain the miRNA-665-induced development of heart failure." (PMID 34639160, 2021). "Additionally, a clinical trial showed that hypoglycemic agents, such as GLP-1R agonists and DPP-4 inhibitors, could not reduce the risk of heart failure." (PMID 35360240, 2022). "Reasons for the discrepancies between these 2 studies of heart failure subjects are unknown but could involve differences in treatment duration, the fact that the former study was open-label and non-randomized, as well as the type of GLP-1R agonist utilized." (PMID 33364978, 2020).
Hypoglycemia (168 papers, 2011 to 2026). A decreased concentration of glucose in the blood. "Treatment with glucagon-like peptide-1 receptor agonists (GLP-1RAs) is associated with low hypoglycemia risk due to enhancement of insulin secretion that is glucose-dependent and preserved glucagon response to hypoglycemia." (PMID 40964167, 2025). "The findings highlight the potential of Ex-D3 as a parent peptide for developing improved GLP-1R imaging probes with a reduced risk of hypoglycemia." (PMID 40076236, 2025). "Owing to the complexity of the GLP‐1R pathway function, we focused on its possible side effects other than neuroprotection, such as hypoglycemia and weight loss, to ensure medication safety." (PMID 37353947, 2023). "Glucagon-like peptide-1 receptor agonists (GLP-1 RA) are incretin mimetics that reduce blood glucose levels with a low associated risk of hypoglycaemia." (PMID 34315528, 2021). "Of importance to glycemic control in T2DM, GLP-1 acts on the islet β-cell GLP-1R to potentiate insulin secretion in a glucose-dependent manner, greatly reducing the risk for hypoglycemia compared to other insulin secretagogues." (PMID 33364978, 2020). "GLP-1R agonist is a novel diabetic medication, which has been proven to be safer than basic insulin with a lower risk of hypoglycemia." (PMID 30953513, 2019). "Given the reduced risk for hypoglycemia with the glucagon-like peptide-1 receptor agonists relative to insulin and sulfonylureas, the former was added in some cases in order to withdraw the latter two." (PMID 30291062, 2017). "The good safety and tolerability of the GLP-1R agonists and DPP-4 inhibitors are well documented leading the AACE/ACE guidelines to conclude that the GLP-1R agonists are safer than sulfonylureas or glinides with respect to the risk of hypoglycemia." (PMID 22390369, 2012). "Sixteen patients were enrolled in a trial comparing the change in FPG and risk of hypoglycemia during 6 weeks of SU monotherapy (glimepiride) and 6 weeks of glucagon-like peptide-1 receptor agonist (GLP1RA) monotherapy (liraglutide) with a 1-week washout between medications." (PMID 39025920, 2024). "Notably, the combination of SU plus glucagon-like peptide-1 receptor agonist (GLP-1RA) was associated with the most significant increase in the risk of hypoglycemia." (PMID 30148851, 2018). "Interestingly, GLP-1R agonists are associated with minimal risk of hypoglycaemia, since their metabolic effects are glucose-dependent." (PMID 27305000, 2016). "Conversely to insulin and other oral anti-T2D, the risk of hypoglycemia was also low and comparable between GLP-1R agonists and DPP-IV inhibitors, thereby constituting an additional advantage for their possible application in AD treatment, as further discussed in the next section." (PMID 25071725, 2014). "However, the glucose-independent activity of some common therapies such as insulin glargine and glimepiride is associated with increased rates of hypoglycaemia compared to GLP-1R agonists." (PMID 22776039, 2013). "Other treatment options for patients with T2D such as metformin, glucagon-like peptide 1 receptor agonists, dipeptidyl peptidase-4 inhibitors, pioglitazone, and sodium-glucose co-transporter-2 inhibitors show in contrast beneficial effects in reducing the risk of hypoglycemia." (PMID 38397994, 2024). "The clinical relevance of avexitide’s GLP-1R antagonism is underscored by its therapeutic use in treating postbariatric hypoglycemia (PBH), a condition characterized by excessive insulin secretion following gastric bypass surgery." (PMID 41226200, 2025). "These interactions are believed to be key contributors to glucagon-like peptide-1 receptor agonist-induced hypoglycemia." (PMID 40429740, 2025). "Clinical trials indicate that gastrointestinal adverse effects are commonly experienced and severe hypoglycemia is rare; however, there is little data regarding glucagon-like peptide-1 receptor agonist in overdose." (PMID 38861153, 2024).
Hypoglycemia (continued). "Hypoglycemia was rare but occurred in the setting of a single agent glucagon-like peptide-1 receptor agonist exposure in two patients." (PMID 38861153, 2024). "In the first study with continuous infusion of GLP-1 receptor (GLP1R) antagonist, exendin 9-39, nine patients with PPH were submitted to mixed-meal tolerance test and all had their hypoglycemia corrected by administration of the GLP1R antagonist." (PMID 36748934, 2023). "Of note that these two studies were performed before the development of the new drugs with few severe hypoglycaemia adverse events such as SGLT2is and glucagon-like peptide-1 receptor agonists (GLP-1 RAs)." (PMID 37234376, 2023). "In contrast, the GLP-1 receptor (GLP-1R) is thought to be one of the most important potential drug targets for glucose-dependent T2DM treatment, lowering hypoglycemia risk compared to insulin and sulfonylureas." (PMID 36677809, 2023). "While both insulin and glucagon-like peptide-1 receptor agonists (GLP-1 RAs) have proven effective in glycemic control for T2DM, insulin use carries the risk of hypoglycemia." (PMID 37779743, 2023). "Several clinical trials have shown that patients receiving combination therapy of a GLP-1R agonist and sulfonylurea (SU), a KATP inhibitor, have a higher incidence of hypoglycemia than those treated with a GLP-1R agonist only." (PMID 36139067, 2022). "Although insulin and glucagon like peptide-1 receptor agonist (GLP-1 RA) exert a good role in glycemic control in T2DM, unfortunately insulin has the risk of triggering hypoglycemia." (PMID 36119737, 2022). "Regarding its glucose-lowering actions in T2DM, GLP-1 stimulates the islet β-cell GLP-1R to potentiate insulin secretion in a glucose-dependent manner, and thus the GLP-1R agonist drug class harbors low overall risk for hypoglycemia." (PMID 35832485, 2022). "The high GLP-1R expression was confirmed on the tissue after the pancreatectomy that resolved the hypoglycemia." (PMID 31903131, 2020). "Glucagon like peptide 1 receptor agonists (GLP-1 RAs) are also effective in terms of glycemic control and associated with weight loss and low risk of hypoglycemia." (PMID 29636825, 2018). "On the other hand, glucagon like peptide 1 receptor agonists (GLP-1 RAs) are also effective in terms of glycemic control (both fasting and postprandial) and associated with weight loss and low risk of hypoglycemia." (PMID 29636825, 2018). "Blocking GLP-1r corrected hypoglycemia in a group of subjects with GB-related postprandial neuroglycopenic hypoglycemia, and the contribution of GLP-1 to postprandial insulin secretion was larger in affected individuals compared to asymptomatic RYGB subjects." (PMID 24951252, 2014). "A low incidence of hypoglycemia is observed with the GLP-1R agonists and DPP-4 inhibitors, likely because of their glucose-dependent actions on insulin and glucagon secretion." (PMID 22390369, 2012). "For this reason, the ADA/EASD consensus statement recommends a GLP-1R agonist when hypoglycemia is a major concern, such as for those who have hazardous jobs and weight loss is beneficial." (PMID 22390369, 2012). "The relatively new antidiabetic drug class glucagon-like peptide 1 receptor agonists (GLP-1 RAs) stimulate β-cells to secrete more insulin without causing hypoglycemia." (PMID 40760325, 2025). "The new generation of glucose-lowering medications, such as glucagon-like peptide 1 receptor agonists (GLP-1RA), dipeptidyl peptidase-4 (DPP-4) inhibitors and sodium-glucose cotransporter 2 (SGLT-2) inhibitors may pose a lower risk for hypoglycaemia." (PMID 39407915, 2024). "SGLT2-I and Glucagon-Like Peptide-1 Receptor Agonists (GLP1-RA) would seem to be the solution to this problem, as they reduce the risk of hypoglycemia and have cardioprotective pleiotropic effects not only in the cardiovascular prevention, but also in acute conditions, such as ACS." (PMID 37341768, 2023).